EIF2S2 (eukaryotic translation initiation factor 2 subunit beta)
Description:
Component of the eIF2 complex that functions in the early steps of protein synthesis by forming a ternary complex with GTP and initiator tRNA. This complex binds to a 40S ribosomal subunit, followed by mRNA binding to form the 43S pre-initiation complex (43S PIC). Junction of the 60S ribosomal subunit to form the 80S initiation complex is preceded by hydrolysis of the GTP bound to eIF2 and release of an eIF2-GDP binary complex. In order for eIF2 to recycle and catalyze another round of initiation, the GDP bound to eIF2 must exchange with GTP by way of a reaction catalyzed by eIF2B (By similarity).
Synonyms: EIF2B; EIF2beta; PPP1R67; EIF2; eIF-2-beta
Tractability: Small molecule: a structure with a bound ligand is known. PROTAC: UniProt records ubiquitination sites on it; ubiquitination databases record sites on it; its protein half-life has been measured.
Gene: Protein-coding gene on chromosome 20 (34,088,309 to 34,112,279, reverse strand). Ensembl gene ENSG00000125977.
Subcellular location: Cytoplasm, cytosol
Subcellular location (Human Protein Atlas): Endoplasmic reticulum; Cytosol
Pathways (Reactome):
Metabolism of proteins: Formation of the ternary complex, and subsequently, the 43S complex; GTP hydrolysis and joining of the 60S ribosomal subunit; L13a-mediated translational silencing of Ceruloplasmin expression; Recycling of eIF2:GDP; Ribosomal scanning and start codon recognition; Translation initiation complex formation
Cellular responses to stimuli: Cellular response to mitochondrial stress; PERK regulates gene expression; Response of EIF2AK1 (HRI) to heme deficiency; Response of EIF2AK4 (GCN2) to amino acid deficiency
Immune System: PKR-mediated signaling
Transport of small molecules: ABC-family protein mediated transport
Gene Ontology:
Molecular function: protein binding; RNA binding; translation initiation factor activity; mRNA binding; translation factor activity, RNA binding; translation initiation factor binding
Biological process: cytoplasmic translational initiation; translational initiation; formation of translation preinitiation complex; regulation of translational initiation
Cellular component: cytoplasm; eukaryotic translation initiation factor 2 complex; nucleus; cytosol; synapse
Genetic constraint (gnomAD): Loss-of-function variants: 4 observed, 35.04 expected, observed/expected ratio (o/e) 0.11, 90% interval 0.055 to 0.26. The upper end of that interval is the gene's LOEUF score, 0.26, which puts it in group 1 of 6, group 1 being the genes least tolerant of losing a copy. Missense variants: 152 observed, 352.68 expected, observed/expected ratio (o/e) 0.43, 90% interval 0.38 to 0.49. Synonymous variants: 101 observed, 116.43 expected, observed/expected ratio (o/e) 0.87, 90% interval 0.74 to 1.02.
Homologues: Orthologues: chimpanzee EIF2S2 (100% identical), macaque EIF2S2 (99% identical), pig EIF2S2 (98% identical), dog EIF2S2 (98% identical), guinea pig EIF2S2 (98% identical), rabbit EIF2S2 (98% identical), rat Eif2s2 (97% identical), mouse Eif2s2 (95% identical), tropical clawed frog eif2s2 (87% identical), zebrafish eif2s2 (77% identical), Drosophila melanogaster eIF2beta (57% identical).
Diseases named in the same sentence as EIF2S2 in open-access papers:
EIF2S2 is named in the same sentence as 28 diseases in open-access papers, as found by Europe PMC text mining. Sharing a sentence is not in itself a finding about the gene and the disease. The quoted sentences say what the papers report.
cancer of male genital organs (2 papers, 2022 to 2024). "Therefore, we further verified the role of EIF2S2 in prostate carcinogenesis." (PMID 35265669, 2022).
colon cancer (2 papers, 2021 to 2022). "We describe the effect of EIF2S2 knockdown on lactate production and the mRNA levels of glycolysis-related genes in human colon cancer SW480 cells." (PMID 34475997, 2021). "The TIMER 2.0 database showed that compared with normal samples, EIF2S2 was overexpressed in most types of cancer, including HCC, colon cancer, lung adenocarcinoma, prostate cancer, endometrial cancer, breast invasive cancer, etc.." (PMID 36276981, 2022).
endometrial cancer (2 papers, 2022). Primary or metastatic malignant neoplasm involving the endometrium (mucous membrane that lines the endometrial cavity). "We created an LLPS-related predictive model for endometrial cancer by extensive study, and it consists of four genes: EIF2S2, SNRPC, PRELID1, and NDUFB9." (PMID 36185238, 2022). "EIF2S2, SNRPC, PRELID1, and NDUFB9 were all up-regulated in endometrial cancer tissues, according to PCR results." (PMID 36185238, 2022). "SNRPC, PRELID1, EIF2S2, and NDUFB9, four of the model’s genes, were discovered to have higher levels of expression in endometrial cancer than in nearby tissues (*P<0.05, **P<0.01, ***P<0.001)." (PMID 36185238, 2022).
germ cell tumor (2 papers, 2019 to 2022). A benign or malignant, gonadal or extragonadal neoplasm that originates from germ cells. "Previous studies have shown that EIF2S2 deletion reduces the incidence of human testicular germ cells in a mouse model of testicular germ cell tumor development, which also suggests that EIF2S2 is involved in cell proliferation and differentiation." (PMID 36276981, 2022). "The deletion of EIF2S2 gene has been reported with suppression of testicular germ cell tumor incidence and recessive lethality in mice." (PMID 31244774, 2019).
prostate carcinoma (2 papers, 2022). A carcinoma that arises from epithelial cells of the prostate gland. "Our experimental evidences demonstrated that EIF2S2 accelerated proliferation, invasion, and migration in prostate cancer cells, indicative of the tumorigenic function of EIF2S2 in prostate cancer." (PMID 35265669, 2022). "These experimental evidences confirmed the carcinogenic roles of EIF2S2 in prostate cancer." (PMID 35265669, 2022). "Among EIF2S2, ARGLU1, and AP000844.2, at present, there is still a lack of experimental evidence to confirm the role of EIF2S2 in prostate cancer." (PMID 35265669, 2022). "Considering the influence of ageing on the heterogeneity of prostate cancer as well as clinical prognosis, an ageing-derived gene signature comprised of ARGLU1, EIF2S2, and AP000844.2 was conducted based on WGNCA, random forest, and uni- and multivariate cox regression models." (PMID 35265669, 2022).
alopecia (1 paper, 2019). Hair loss usually from the scalp. "Although the SNP is not far from the RALY gene, it mapped within the EIF2S2 gene, which has been shown to be involved in protection against chemotherapy-induced alopecia." (PMID 31708969, 2019).
cervical cancer (1 paper, 2019). A primary or metastatic malignant neoplasm involving the cervix. "It is also reported that EIF2S2 is up-regulated and involved in major enriched genes in epithelial ovarian carcinoma (EOC) samples and cervical cancer vs. normal group." (PMID 31244774, 2019).
colorectal cancer (1 paper, 2021). A primary or metastatic malignant neoplasm that affects the colon or rectum. "The correlation between EIF2S2 and 18F-FDG uptake in colorectal cancer and the effect of EIF2S2 knockdown on the levels of genes related to lactate production and partial glycolysis in SW480 cells were investigated." (PMID 34475997, 2021).
glioma (1 paper, 2019). A benign or malignant brain and spinal cord tumor that arises from glial cells (astrocytes, oligodendrocytes, ependymal cells). "EIF2S2 and EIF2S3, on the other hand, are both upregulated in gliomas with the γ isoform being the only subunit to be overexpressed in the mesenchymal GBM subtype compared to non-tumoral tissue." (PMID 31795417, 2019).
liver cancer (1 paper, 2022). An epithelial or non-epithelial malignant neoplasm that arises from the liver. "We studied the role of EIF2S2 in the malignant progression of liver cancer and its relationship with immune infiltration." (PMID 36276981, 2022).
lung adenocarcinoma (1 paper, 2022). A carcinoma that arises from the lung and is characterized by the presence of malignant glandular epithelial cells. "At the same time, EIF2S2 gene is also found to be highly expressed in lung cancer, which can predict the prognosis of lung adenocarcinoma patients." (PMID 36276981, 2022).
melanoma (1 paper, 2015). A malignant, usually aggressive tumor composed of atypical, neoplastic melanocytes. "The ASIP region is one of four known melanoma-susceptibility regions and includes the four genes (RALY, EIF2S2, CHMP4B and ASIP)." (PMID 26083354, 2015).
teratoma (1 paper, 2023). A non-seminomatous germ cell tumor characterized by the presence of various tissues which correspond to the different germinal layers (endoderm, mesoderm, and ectoderm). "Although full deficiency for Eif2s2 was embryonic lethal, partial deficiency protected against teratomas by restricting germ cell proliferation and differentiation." (PMID 36857387, 2023).
testicular germ cell tumours (1 paper, 2019). "Marker genes for pro-spermatogonia included Eif2s2, which has been linked to testicular germ cell tumours, that originate from pro-spermatogonia." (PMID 30890697, 2019).
Turner syndrome (1 paper, 2024). Turner syndrome is a chromosomal disorder associated with the complete or partial absence of an X chromosome. "A recent clinical study reports that patients with Turner syndrome exhibit a lack of a cluster of oogonia with high EIF2S2 expression and germ cell apoptosis at 12–13 weeks post‐conception, subsequently developing POI after birth." (PMID 39044637, 2024).
cancer (11 papers, 2006 to 2026). A tumor composed of atypical neoplastic, often pleomorphic cells that invade other tissues. "Typically, cancer cells rely on aerobic glycolysis (the Warburg effect) for energy, and knocking out EIF2S2 reduces the expression of glycolysis-related genes." (PMID 35669725, 2022). "EIF2S2 activated the Wnt signaling pathways to drive cancer development by regulating the interaction of LINC01600 with Myc protein." (PMID 35669725, 2022). "The need for accelerated protein synthesis in cancer cells is reflected by the up-regulation of the translation initiation factor EIF2S2." (PMID 16982006, 2006). "Similarly, the expression of EIF2S2 mRNA in cancer samples was also significantly increased in 50 paired cases of HCC tissues and adjacent normal tissues (p < 0.001)." (PMID 36276981, 2022). "Moreover, some other genes including AKT, c-myc, MCM4, and EIF2S2 were also significantly elevated in cancer tissues." (PMID 36497260, 2022). "According to certain studies, the four model genes EIF2S2, SNRPC, PRELID1, and NDUFB9 have significant roles in the development of cancer." (PMID 36185238, 2022). "EIF2S2 is an anabolic factor, while PSMD1 is a catabolic factor, both of which are correlated to poor cancer prognosis." (PMID 33379356, 2020).
tumor (8 papers, 2016 to 2022). "Our study shows that EIF2S2 is associated with a variety of immune cells, which may promote tumor proliferation and metastasis by promoting immune infiltration of HCC." (PMID 36276981, 2022). "Based on the drug sensitivity data from the GDSC database, we predicted the chemosensitivity of each tumor sample by the R software package “pRRophetic” to further explore the correlation between EIF2S2 and common antitumor drug sensitivity." (PMID 36276981, 2022). "The expression of EIF2S2 was significantly enriched in cytokine receptors, indicating that EIF2S2 was involved in tumor development and immunotherapy." (PMID 36276981, 2022). "In CRC, tumor tissues with high expression of EIF2S2 had a significantly higher SUVmax than tissues with low expression (25.6 ± 11.29 vs 16.56 ± 6.39) (P <0.05)." (PMID 34475997, 2021). "The positive rate of EIF2S2 expression in tumor tissues is 97.6% (41/42) and 0% (0/10) in adjacent normal tissues." (PMID 34475997, 2021). "For example, Celf1 promotes expression of Cebpb via interacting with Eif2s1 and Eif2s2 in proliferating livers and in tumor cells." (PMID 32546682, 2020). "Studies have shown that the PI3K/Akt/GSK-3β/ROS/EIF2S2 pathway could regulate NK cell activity and tumor cell sensitivity to NK cells, leading to breast cancer growth and lung metastasis." (PMID 36276981, 2022). "EIF2S1, EIF2S2, and EIF2S3 were all reported to associate tumor progression." (PMID 31258820, 2019). "Through immunohistochemical staining of the tissues of 42 patients with CRC, we found that EIF2S2 and GLUT1 were more highly expressed in tumor tissues than in adjacent normal tissues." (PMID 34475997, 2021). "That EIF2S2 expression is not related to age, sex, tumor differentiation, or tumor stage, is consistent with the data from the UALCAN database." (PMID 34475997, 2021). "The TN clusters (TN and TN+Her2) include proliferative proteins (MCM3 and 5), translation related proteins (RCL1, MRPS27, EIF2S2 and EEF1G) and metabolic enzymes (glutaminase and hexokinase 2), which reflect the higher dependence on glutamine and glucose of TN versus the other tumours." (PMID 26725330, 2016). "The average staining intensity scores of EIF2S2 and GLUT1 in tumor tissues were significantly higher than those in adjacent normal tissues (P <0.001)." (PMID 34475997, 2021).
infection (2 papers, 2014 to 2021). The state of being infected such as from the introduction of a foreign agent such as serum, vaccine, antigenic substance or organism. "Next, 293 T cells were transfected with 50 nM eIF2S2 siRNA for 72 h or treated with 10 μM tomatidine for 2 h prior to transfection with 5 μg of TC-83 RNA containing the mutated stop codon or infection with the nano Luciferase expressing TC-83 virus (TaV-nLuc)." (PMID 34452398, 2021). "Experimental rescreening of the subunits in this complex indicated that EIF2S2 is the important subunit for infection." (PMID 24817247, 2014).
EIF2S2 also shares sentences with these, for which no sentence is quoted: anxiety disorder (1 paper); basal cell carcinoma (1); breast carcinoma (1); breast invasive cancer (1); cancer of female genital organs (1); cataract (1); head and neck squamous cell carcinoma (1); hepatocellular carcinoma (1); prostate (1); skin cancer (1).